COL11A2 (collagen type XI alpha 2 chain)
Description:
May play an important role in fibrillogenesis by controlling lateral growth of collagen II fibrils.
Synonyms: HKE5; DFNA13; DFNB53; FBCG2; OSMEDA; OSMEDB; PARP; STL3
Tractability: Antibody: its Gene Ontology location is reachable by antibodies, with high confidence; UniProt places it where antibodies can reach, with medium confidence; UniProt predicts a signal peptide or a membrane-spanning region. Other modalities: an approved drug acts on it.
Gene: Protein-coding gene on chromosome 6 (33,162,681 to 33,192,766, reverse strand). Ensembl gene ENSG00000204248.
Subcellular location: Secreted, extracellular space, extracellular matrix
Pathways (Reactome):
Extracellular matrix organization: Assembly of collagen fibrils and other multimeric structures; Collagen biosynthesis and modifying enzymes; Collagen chain trimerization; Collagen degradation; Non-integrin membrane-ECM interactions
Developmental Biology: Developmental Lineage of Pancreatic Ductal Cells
Signal Transduction: MET activates PTK2 signaling
Gene Ontology:
Molecular function: extracellular matrix structural constituent conferring tensile strength; protein binding; protein-macromolecule adaptor activity; extracellular matrix structural constituent
Biological process: cartilage development; collagen fibril organization; roof of mouth development; sensory perception of sound; skeletal system development; soft palate development; skeletal system morphogenesis
Cellular component: extracellular matrix; collagen type XI trimer; endoplasmic reticulum lumen; extracellular region; collagen trimer
Genetic constraint (gnomAD): Loss-of-function variants: 114 observed, 264.84 expected, observed/expected ratio (o/e) 0.43, 90% interval 0.37 to 0.5. The upper end of that interval is the gene's LOEUF score, 0.5, which puts it in group 2 of 6, group 1 being the genes least tolerant of losing a copy. Missense variants: 1,834 observed, 2,279.1 expected, observed/expected ratio (o/e) 0.8, 90% interval 0.77 to 0.84. Synonymous variants: 771 observed, 852.23 expected, observed/expected ratio (o/e) 0.9, 90% interval 0.85 to 0.96.
Gene-disease validity (ClinGen):
ClinGen rates the evidence that COL11A2 causes each of these diseases.
nonsyndromic genetic hearing loss (autosomal dominant): Definitive. A disease characterized by hearing loss that is not part of a larger syndrome.
otospondylomegaepiphyseal dysplasia (autosomal dominant; autosomal recessive): Definitive. An inborn error of cartilage collagen formation characterized by sensorineural hearing loss, enlarged epiphyses, skeletal dysplasia with disproportionately short limbs, vertebral body anomalies and a characteristic facies.
nonsyndromic genetic hearing loss (autosomal recessive): Moderate.
Homologues: Orthologues: chimpanzee COL11A2 (99% identical), pig COL11A2 (96% identical), dog COL11A2 (96% identical), macaque COL11A2 (95% identical), mouse Col11a2 (95% identical), rat Col11a2 (94% identical), guinea pig COL11A2 (92% identical), rabbit COL11A2 (92% identical), tropical clawed frog col11a2 (73% identical), zebrafish col11a2 (72% identical). Paralogues in human: COL5A1 (69% identical), COL11A1 (67% identical), COL5A3 (55% identical), COL27A1 (36% identical), COL2A1 (36% identical), COL1A1 (35% identical), COL3A1 (34% identical), COL24A1 (34% identical), COL4A5 (34% identical), COL5A2 (34% identical), COL4A1 (33% identical), COL1A2 (32% identical), and 25 more.
Diseases named in the same sentence as COL11A2 in open-access papers:
COL11A2 is named in the same sentence as 85 diseases in open-access papers, as found by Europe PMC text mining. Sharing a sentence is not in itself a finding about the gene and the disease. The quoted sentences say what the papers report.
Stickler syndrome (27 papers, 2005 to 2025). Stickler syndrome is an inherited vitreoretinopathy characterized by the association of ocular signs with more or less complete forms of Pierre-Robin sequence, bone disorders, and sensorineural deafness (10% of cases). "COL11A2 is associated with several skeletal dysplasia diseases, including fibrochondrogenesis and Stickler syndrome, which is characterized by cartilage destabilization and abnormal skeletal shape and properties." (PMID 40554768, 2025). "COL11A1- and COL11A2-related Stickler syndrome results in more frequent hearing loss, being moderate and involving all frequencies." (PMID 36140739, 2022). "Mutations in COL11A2 have been associated with non-syndromic deafness, otospondylomegaepiphyseal dysplasia, Weissenbacher-Zweymüller syndrome, and Stickler syndrome (OMIM ID *120290)." (PMID 21814517, 2011). "Mutations of gene COL11A2 cause both DFNA13 (6p21), such as Stickler syndrome Type 2 (STL2 – 6p21.3, progressive myopia, early vitreo-retina and articular degeneration, facial hypoplasia, deafness)." (PMID 16446920, 2005). "Some years later, disease-causing mutations in the COL11A1 and COL11A2 gene could also be associated with a Stickler syndrome phenotype." (PMID 36140739, 2022). "Notably, in humans, mutations in COL11A2 lead to Stickler syndrome, a condition associated with craniofacial dysplasias, and joint abnormalities that lead to premature OA whilst in mutant mice the cartilage degradation phenotype appears to be milder." (PMID 35057801, 2022). "However, in the case of Stickler syndrome caused by COL11A2, it has been reported that the ocular phenotype and vitreous are normal." (PMID 34680973, 2021). "In addition, abnormal COL11A2 gene structure was also associated with Marshall’s or Stickler syndrome marked with skeletal dysplasia and joint pain." (PMID 32396528, 2020). "Mutations in the type XI collagen genes col11a1 and col11a2 have previously been linked to numerous skeletal dysplasias, such as Stickler syndrome and fibrochondrogenesis, which are associated with cartilage destabilization, and abnormal skeletal shape and properties." (PMID 30249781, 2018). "Mutations in the COL2A1, COL11A1, and COL11A2 procollagen genes cause Stickler syndrome." (PMID 28841907, 2017). "Similarly, mutations in the collagen-α chain genes, COL2A1, COL9A2, COL11A1, and COL11A2, have been associated with different forms of Stickler syndrome (OMIM#108300, #614284, #604841, and #184840, respectively), a clinically variable condition that includes cleft palate." (PMID 28106045, 2017). "By contrast, Stickler syndrome has the most collagens (six) linked to this syndrome (COL2A1, COL9A1, COL9A2, COL9A3, COL11A1, and COL11A2), followed by Ullrich congenital muscular dystrophy, with four collagens associated (COL6A1, COL6A2, COL6A3, and COL12A1)." (PMID 37189830, 2023). "Note that COL11A2 heterotrimer partner COL11A1 is associated with both eBMD and OA traits and causes Stickler syndrome with fragility fractures." (PMID 35057801, 2022). "The boy (P.23) with a COL11A2 splice site alteration was characterized by Stickler syndrome (MIM #108300) with congenital cataract, sensorineural deafness, relatively short extremities with elbows valgus and joints pain, and typical midface hypoplasia." (PMID 35250876, 2022). "Stickler syndrome caused by COL2A1, COL11A1, and COL11A2 genes has a dominant inheritance, whereas COL9A1, COL9A2, and COL9A3 genes show a recessive inheritance." (PMID 34680973, 2021). "The known causative genes of Stickler syndrome are COL2A1, COL11A1, COL11A2, COL9A1, COL9A2, and COL9A3." (PMID 34680973, 2021). "To date, mutations in seven genes (COL2A1, COL11A1, COL11A2, COL9A1, COL9A2, COL9A3, and LOXL3) have been reported to cause Stickler syndrome." (PMID 32756486, 2020). "With regard to Stickler syndrome, we identified pathogenic variants in the COL11A1 (two cases) and COL11A2 (one case) genes." (PMID 31427586, 2019).
Stickler syndrome (continued). "To date, multiple mutations in the collagen-encoding genes COL2A1, COL11A1, COL11A2, COL9A1, COL9A2, and COL9A3 have been associated with six genetically distinct types of Stickler syndrome." (PMID 28335520, 2017). "In humans, Stickler syndrome caused by mutations of COL2A1, COL11A1, COL11A2, COL9A1 and COL9A2, is one of the most common connective tissue disorders characterized by ocular, skeletal, orofacial and auditory defects." (PMID 26307084, 2015). "Stickler syndrome is commonly caused by mutations in different collagen genes, namely COL2A1, COL11A1 and COL11A2 (autosomal dominant inheritance) and COL9A1 and COL9A2 (autosomal recessive inheritance)." (PMID 26307084, 2015). "The Stickler syndrome-related collagens, Col2a1, Col11a1, and Col11a2, are important components of both the cochlear TM and cartilage." (PMID 22567353, 2011). "Mutations in COL11A2 were reported to cause many inherited skeletal disorders like autosomal recessive otospondylomegaepiphyseal dysplasia (OSMED) (OMIM#215150) and Marshall’s or Stickler syndrome (OMIM#184840)." (PMID 32396528, 2020). "First, this study included patients with initial signs of high myopia or retinal detachment; however, COL11A2 mutations have been reported in non-ocular Stickler syndrome." (PMID 32756486, 2020). "Indeed, mutations in COL2A1, COL11A1, COL11A2, COL9A1, COL9A2, and COL9A3 have been associated with Stickler syndrome and early-onset OA." (PMID 28335520, 2017). "A COL11A2 mutation was linked to autosomal dominant NSHL and Stickler syndrome in human." (PMID 22567353, 2011). "Variants of Stickler syndrome have been designated STL1 (vitreous type with mutations in COL2A1 gene), STL2 (early onset hearing loss and mutations in the COL 11A1 gene) and STL3 (non-ocular type caused by mutations in the COL11A2 gene)." (PMID 18950500, 2008).
hearing loss (17 papers, 2012 to 2025). "Previous research has explored possible genetic links to middle-ear conditions through COL11A2-related hearing loss and heritable estimates from twin studies." (PMID 41515579, 2025). "TRIOBP, MYO6, and COL11A2 were found in both clinical gene sets (otoscope and clingen), and common variant studies of hearing loss (GWAS)." (PMID 38943082, 2024). "Variants in the COL11A2 gene, which encodes collagen type XI alpha 2 chain, has been reported to cause hearing loss and has been associated with osteoarthritis and ossification of the posterior longitudinal ligament of the spine." (PMID 35363175, 2022). "Several collagen genes (COL1A1, COL1A2, COL2A1, COL4A3, COL4A4, COL4A5, COL11A1, and COL11A2) are associated with hereditary syndromic hearing loss." (PMID 33848312, 2021). "Both Ceacam16 and Col11A2 encode proteins that are components of the tectorial membrane (TM), and their deletion disrupts TM structure, resulting in hearing loss." (PMID 29073148, 2017). "Col11a2 deficient mice are smaller than wildtype littermates and also show a skeletal dysplasia with hearing impairment." (PMID 23527306, 2013). "Overall, mutations in COL11A1 (82.5%) and COL11A2 (94.1%) seem to be more frequently associated with hearing impairment than mutations in COL2A1 (52.2%)." (PMID 23110709, 2012). "Mutations in COL11A1 and COL11A2 have been shown to cause nonsyndromic hereditary hearing loss." (PMID 33848312, 2021). "The loudness growth curves in the MWS family are comparable to those of patients with intra-cochlear conductive hearing loss, such as DFNA8/12 (caused by TECTA gene variants) and DFNA13 (COL11A2 gene), which are caused by tectorial membrane abnormalities." (PMID 35572943, 2022). "The COL11A1 and COL11A2 proteins have been reported in the developing mouse cochlear and in a mouse model, COL11A1 haploinsufficiency does not cause significant hearing loss, whereas in humans haploinsufficiency has been reported to cause mild hearing loss." (PMID 32901364, 2021).
deafness (14 papers, 2005 to 2026). An inherited or acquired condition characterized by the complete loss of the ability to hear from one or both ears. "Col11a2 is a collagen gene whose function loss is associated with various syndromes involving deafness." (PMID 39558975, 2024). "For example, COL11A2 is related to genetic hearing loss and deafness, which is also consistent with some of the phenotypes in our nIHH patients." (PMID 37679557, 2024). "Mutations of COL11A2 result in deafness in patients with DFNA13 (non-syndromic sensorineural deafness type 13)." (PMID 36118891, 2022). "WES confirmed compound heterozygous COL11A2 variants which cause a spectrum of disorders from mild deafness to OSMED to potentially lethal FBCG2." (PMID 34092239, 2021). "So far, all previous data on genotype-phenotype correlations for COL11A2 variants suggested that functional variations in this gene lead to either moderate to severe deafness and/or moderate to severe skeletal dysplasias." (PMID 23527306, 2013). "Deletion of COL11A2 gene in mice exhibit developmental defects, such as small body, deafness, and disorganized growth plate in long bones." (PMID 40808558, 2026). "Mutations in the COL11A2 gene are associated with type III Stickler syndrome, otospondylomegaepiphyseal dysplasia (OSMED syndrome), Weissenbacher-Zweymuller syndrome, autosomal dominant non-syndromic sensorineural type 13 deafness (DFNA13), and DFNB 53 deafness (DFNB53)." (PMID 35573665, 2022).
otospondylomegaepiphyseal dysplasia (11 papers, 2011 to 2025). "Mutation in the human COL11A2 gene has been found to cause otospondylomegaepiphyseal dysplasia, a disorder characterised by a variety of skeletal abnormalities including young onset OA." (PMID 38041181, 2023). "COL11A2 mutations are also associated with a lot of inherited skeletal diseases, whereby Otospondylomegaepiphyseal dysplasia (OSMED) is autosomal recessive disease, featuring auditory dysfunction and short asymmetrical limbs." (PMID 32396528, 2020). "The remaining COL11A2-related STL type 3 (OMIM#184840) is also referred to as otospondylomegaepiphyseal dysplasia (OSMED)." (PMID 40919431, 2025). "In the catalog (CD−M7), Pou3f4, Homer2, and Col11a2 were associated with NSHL, Snai2 with Waardenburg syndrome, Lars2 with Perrault syndrome, and Col11a2 with otospondylomegaepiphyseal dysplasia." (PMID 39684410, 2024). "Type 2 SS and the SS variant otospondylomegaepiphyseal dysplasia (OSMED) are caused by deleterious variants in COL11A1 and COL11A2, respectively." (PMID 33348901, 2020). "Type 3 SS is an ultra-rare disease, known as non-ocular SS or otospondylomegaepiphyseal dysplasia (OSMED) with only a few pathogenic COL11A2 variants reported to date." (PMID 37347055, 2023).
type III Stickler syndrome (6 papers, 2011 to 2022). "In fact, the human orthologue of col11a2 also cause type III Stickler syndrome when mutated, and this disorder is characterised by early-onset OA." (PMID 35057801, 2022). "One C to T transition in exon 56, which led to premature translation termination codon in COL11A2 (R845X), was also reported in individuals with Weissenbacher-Zweymuller syndrome." (PMID 32396528, 2020). "Type I Stickler syndrome (STL1) is associated with mutations in the COL2A1 gene encoding type II collagen, while mutations in COL11A1 and COL11A2 encoding type XI collagen, are associated with type II (STL2) and type III Stickler syndrome (STL3) respectively." (PMID 23110709, 2012).
myopia (4 papers, 2005 to 2022). "Taken together, scleral Col1a1, Col4a3, Col8a2, Col11a2, and Col15a1 expression were regulated through ER stress during the myopia progression." (PMID 36216837, 2022). "Seventy-five percent of cases (6/8) had a cleft palate or uvula bifida (3/3 with COL11A1 variants, 3/5 with COL11A2 variants), and all three cases with COL11A1 variants had congenital myopia." (PMID 31427586, 2019).
osteoarthritis (4 papers, 2018 to 2024). A noninflammatory degenerative joint disease occurring chiefly in older persons, characterized by degeneration of the articular cartilage, hypertrophy of bone at the margins and changes in the synovial membrane. "We suspect that biallelic COL11A2 variants in trans may have contributed to early development of osteoarthritis in addition to hearing loss." (PMID 35363175, 2022). "The hearing loss and osteoarthritis in this patient may be due to the compound heterozygous variants in the COL11A2 gene, and the conformational changes induced by the variants may have changed the immunogenicity of type XI collagen, leading to the development of RA." (PMID 35363175, 2022). "In particular, we probe the effect of the lack of col11a2 gene in zebrafish, which causes the early onset of osteoarthritis." (PMID 39466814, 2024).
rheumatoid arthritis (4 papers, 2017 to 2024). A chronic, systemic autoimmune disorder characterized by inflammation in the synovial membranes and articular surfaces. "Several polymorphisms (COL11A1 rs3753841 and rs1676486, COL11A2 rs1799907) have been associated with lumbar disc herniation and rheumatoid arthritis." (PMID 28523640, 2017). "The COL11A1 rs3753841 and/or COL11A2 rs1799907 variants have however been associated with lumbar disc herniation, limbus vertebra in gymnasts, lumbar spine stenosis, ossification of the posterior longitudinal ligament of the spine and rheumatoid arthritis." (PMID 36553626, 2022). "Despite the importance of type XI collagen in the joints, association of rheumatoid arthritis (RA) with COL11A2 has not been reported." (PMID 35363175, 2022).
fibrochondrogenesis type 2 (3 papers, 2013 to 2022). "The original diagnosis was ‘mild’ fibrochondrogenesis type 2 (FBCG2; OMIM #614524), which is caused by COL11A2 variants and can be lethal." (PMID 34092239, 2021). "Case 1.4.5 revealed heterozygosity in both partners for likely pathogenic variant in RBBP8 causative of Seckel Syndrome 2 (OMIM # 606744), whereas case 1.4.6 revealed both parents to be heterozygous carriers for a VUS in COL11A2 associated with fibrochondrogenesis 2 (OMIM # 614524)." (PMID 35123515, 2022).
metabolic syndrome (3 papers, 2019 to 2023). A cluster of metabolic risk factors for CARDIOVASCULAR DISEASES and TYPE 2 DIABETES MELLITUS. "Furthermore, in an investigation of SNPs associated with the methylation of COL11A2 genes, two identified rare alleles of these methylation sites showed an association with plasma fasting glucose levels in an obese cohort of metabolic syndrome." (PMID 37886940, 2023). "In the case of COL11A2, two different studies have evaluated the contribution of methylation levels in VAT either in obese individuals with metabolic syndrome or in individuals with insulin resistance." (PMID 33803198, 2021).
Arthritis (2 papers, 2022). Inflammation of a joint. "Studies have shown that the expression of Col11a2 was significantly increased in the cartilage of patients with arthritis, the overexpression of Col11a2 promoted the destruction of articular cartilage and chondrocyte necrosis." (PMID 35864275, 2022).
breast carcinoma (2 papers, 2005 to 2025). "In this group, we found some overexpressed genes; of these, COL11A2 and netrin-2 had not been previously associated with breast cancer." (PMID 16060964, 2005).
cleft palate (2 papers, 2019 to 2021). Cleft palate is a fissure type embryopathy that affects the soft and hard palate to varying degrees. "On the other hand, it has also been found that the COL2A1, COL11A1, and COL11A2 were associated and influence the risk of nonsyndromic forms of cleft palate." (PMID 30924295, 2019). "Previously, two different studies has proposed that major clefting locus might be located at 6p and mutation in several genes such as COL2A1, COL11A1, and COL11A2 caused syndrome that was associated with cleft palate, Robin sequence, and micrognathia." (PMID 30924295, 2019). "Specific to skeletal dysplasia, pathogenic variants in genes encoding type II and XI collagen (COL2A1, COL11A1 and COL11A2), Filamin-A (FLNA), and the diastrophic sulfate transport protein (SLC26A2) are all well-known as being associated with cleft palate." (PMID 33446226, 2021).
disc degeneration (2 papers, 2019 to 2021). "Among which, KRT19 and COL6A2 were considered as important degeneration markers in the previous studies, while the SNPs and mutations of COL11A2 are also linked to disc degeneration." (PMID 33536009, 2021).